LPAR5 (lysophosphatidic acid receptor 5)
Diseases named in the same sentence as LPAR5 in open-access papers (continued):
Sharing a sentence is not in itself a finding about the gene and the disease.
colon cancer (1 paper, 2024). "Moreover, LPAR2 and LPAR5 mediate resistance of colon cancer cells to 5′-fluoro-uracil, whilst in the same tumour type, LPA enhances resistance to EZH2 inhibitors through LPAR2, suggesting that co-targeting of ATX/LPA/LPAR2 and EZH2 might be beneficial for colon cancer treatment." (PMID 38607068, 2024).
endothelial dysfunction (1 paper, 2021). In vascular diseases, endothelial dysfunction is a systemic pathological state of the endothelium (the inner lining of blood vessels) and can be broadly defined as an imbalance between vasodilating and vasoconstricting substances produced by (or acting on) the endothelium. "This study suggested that ox-LDL stimulation reduced CD31, eNOS and NO levels as well as enhanced α-SMA and iNOS expression, which was reversed by LPAR5 silencing, implicating the improving effects of LPAR5 downregulation on ox-LDL-induced endothelial dysfunction." (PMID 34662522, 2021).
itch (1 paper, 2024). "In the present study, we show a segregated localization of LPAR5 in peripheral sensory neurons and LPAR2 in cortical and thalamic neurons and opposing effects of deletion of either LPAR5 or LPAR2 on HCQ-evoked itch responses." (PMID 39125747, 2024). "From these non-subpopulation-specific experiments, we cannot deduce a significant difference but nonetheless, these subtle results are in agreement with other behavioral studies and suggest that LPAs enhance stimulus-evoked itch via the LPAR5 stimulation of sensory neurons." (PMID 39125747, 2024).
ovarian carcinoma (1 paper, 2020). A malignant neoplasm originating from the surface ovarian epithelium. "In line with this study, tumor associated T cells isolated from the ascites of ovarian cancer patients also showed higher expression of LPAR5 and LPAR6, whereas LPAR1-4 expression was comparable to ovarian cancer cells." (PMID 32397679, 2020).
Sepsis (1 paper, 2022). Sepsis is defined as life-threatening organ dysfunction caused by a dysregulated host response to infection. "Therefore, both LPAR5 and LPAR1, but not LPAR2, mediate to some extent the pathogenic effects of ATX/LPA in experimental sepsis." (PMID 35887265, 2022).
tumor (30 papers, 2011 to 2025). "Since we observed improved tumor immunity by Lpar5-deficient CD8 T cells, we sought to determine the Lpar5 receptor contribution on CD8 T cell metabolism." (PMID 37270644, 2023). "Authors showed in a mouse melanoma model that animals receiving LPAR5-deficient tumour-specific CD8 T lymphocytes controlled tumour growth significantly better than animals receiving wild type CD8 T cells." (PMID 28402936, 2017). "And the expression of LPAR5 was associated with tumor stage, size and lymph node metastases." (PMID 29740512, 2018). "Previous reports have shown that CD8+ T cells also express LPAR5, regulating respiration and cytotoxic activity in the tumor microenvironment." (PMID 41502512, 2025). "PARP1 inhibitors can also depress METTL3 expression, resulting in a decreased M6A level of LPAR5 mRNA A1881, consequently leading to decreased stability of LPAR5 mRNA and exhibiting a synergistic effect of tumor growth suppression with radiotherapy." (PMID 38473842, 2024). "To note, a study on mice with melanoma demonstrated that the treatment with LPAR5−/− tumor-specific CD8+ T lymphocytes led to an elevated infiltration of CD8+ T cells in tumors." (PMID 39062979, 2024). "Altogether, we establish LPA signaling through Lpar5 as a potential CD8 T cell directed therapy to improve endogenous anti-tumor immune responses." (PMID 37270644, 2023). "In various cancers, LPAR5 overexpression is involved in the invasion and metastasis of tumor cells, and LPA can inhibit the activation and function of T cells by binding to LPAR513." (PMID 37037831, 2023). "Pharmacological inhibition of ATX, or the downstream receptor LPAR5, in combination with anti–PD-1 was sufficient to restore the antitumor immune response and efficaciously control lung tumor growth in multiple KP tumor models." (PMID 37655662, 2023). "It would be helpful to understand the role of LPAR5 in tumorigenesis from the perspective of clinical tumor samples." (PMID 37037831, 2023). "The expression of LPAR5 varied between multiple tumors and corresponding normal tissues, and was higher in most tumor tissues." (PMID 37037831, 2023). "We found that the pan-LPAR and the LPAR5-specific inhibitors worked equally well in controlling primary tumor growth when combined with anti–PD-1 treatment." (PMID 37655662, 2023). "Previously, our laboratory has shown Lpar5−/− CD8 T cells impede local tumor growth better than wildtype CD8 T cells." (PMID 37270644, 2023). "We propose LPAR5 serves as a lipid-regulated immune checkpoint which impairs anti-tumor immunity through multiple mechanisms that include metabolic reprogramming of tumor-specific CD8 T cells and direct inhibition of antigen receptor-induced T cell activation." (PMID 37270644, 2023). "There was a significant difference in LPAR5 expression between PTC tissue samples (n = 490) and normal thyroid tissue samples (n = 58) (p < 0.001), LPAR5 is highly expressed in tumor tissues." (PMID 37037831, 2023). "Further, LPAR5 expression decreases with increasing tumor purity consistent with LPAR5 expression predominantly restricted to immune cells." (PMID 37270644, 2023). "This study aimed to better understand the role of LPAR5 in anti-tumor immunotherapy in human tumors and to provide a new strategy for anti-tumor therapy." (PMID 37037831, 2023). "But the effect of LPAR5 in the study was reported to mediate by endothelial cells and anti-tumor drugs." (PMID 36591220, 2022). "Our results demonstrate that LPAR5 acts as a key regulator of IR-induced EMT in tumor cells through the ERK/Snail pathway." (PMID 36199069, 2022). "By the comparison between the tumor tissues and paired normal bone tissues, we found that the expression of LPAR5 was higher in the tumor tissues, which was also validated by immunochemical staining." (PMID 36591220, 2022).
tumor (continued). "We observed that knockdown of LPAR5 can significantly inhibit the proliferation and migration of tumor cells, while high expression of LPAR5 can increase the proliferation and inhibit apoptosis of tumor cells after irradiation." (PMID 36199069, 2022). "The higher level of LPAR5 and LPAR6 in tumor tissue most likely reflects the presence of tumor‐associated immune cells, which is consistent with our own data." (PMID 30353652, 2019). "While primary tumor cells express predominantly genes encoding EDG‐type receptors (LPA1‐3), immune cells (TAMs and TATs) also express genes for the non‐EDG receptors LPAR5 and LPAR6 at high levels." (PMID 30353652, 2019). "Therefore, the potential value of LPAR5 in tumor immunology needs to be further investigated in future studies." (PMID 37037831, 2023). "The expression levels of LPAR5 were different between 14 types of tumor and normal samples." (PMID 37037831, 2023). "We will further explore the role of LPAR5 in 33 different tumor types." (PMID 37037831, 2023). "SMAD3-activation of the TGF-ß/Smad3 pathway, which jointly targets ABR and LPAR5, could alter tumor cell function in PTC by suppressing NIS expression and altering tumor cell function." (PMID 37324256, 2023). "Third, LPAR5 as a new immunotherapy target still lacks direct evidence, and it will be necessary to verify whether LPAR5 can inhibit tumor growth or benefit the prognosis of patients through clinical trials of relevant targeted therapies." (PMID 37037831, 2023). "Therefore, this study aimed to explore the role of LPAR5 expression in anti-tumor immunotherapy and its potential targets." (PMID 37037831, 2023). "By immunohistochemical staining, it could be found that LPAR5 was highly expressed in tumor tissues than paraneoplastic tissues (P<0.001), and LPAR5 was expressed both in multi-nucleated cells and mono-nucleated cells." (PMID 36591220, 2022). "In GSE99671 dataset, the expression of LPAR5 was higher in the tumor tissues (P<0.001)." (PMID 36591220, 2022). "Some studies have also reported the pro-tumor effect of LPAR5." (PMID 36591220, 2022). "And this could also explain why the expression of LPAR5 level is higher in tumor tissues than in normal tissues." (PMID 36591220, 2022). "In this regard, we consider that antagonism of LPAR5 signaling by tumor-specific CD8+ T cells may be an important addition to the arsenal of checkpoint inhibitors." (PMID 32397679, 2020). "Taken together, these studies suggest that inhibition of LPAR5 in distinct immune cell types such as CD8+ T cells may boost anti-tumor activity and impede metastasis." (PMID 32397679, 2020). "It is interesting that ATX, LPAR1, and LPAR5 are higher in the immune-high tumor (Cd14-, Cd68-, Cd164-, and Cd3E-high) group, but LPAR2.3 are higher in the immune-low group, suggesting the complex regulatory roles of the ATX–LPA axis in the tumor–immune system interaction." (PMID 31658655, 2019). "Besides, LPAR5 regulates cancer cell proliferation, migration, invasion and tumor immunity." (PMID 39671369, 2024). "To understand the role of LPA in the context of anti-tumor immunity, we performed adoptive transfers using a systemic tumor model with the hypothesis that Lpar5 receptor knockout (Lpar5−/−) CD8 T cells also display an enhanced ability to kill tumor cells systemically in vivo." (PMID 37270644, 2023). "Moreover, overexpression of LPAR5 promotes tumor progression through adsorption mechanisms." (PMID 37037831, 2023). "However, there are few studies on the role of LPAR5 in tumor progression." (PMID 36199069, 2022). "In addition, the clinical detection of LPAR5+ macrophages in surgically resected tumor samples from patients may help in the prediction of tumor metastasis and survival of patients." (PMID 36591220, 2022). "While almost all naive CD8+ T cells express LPAR2, LPAR5, and LPAR6, we next wanted to analyze the expression of these receptors on tumor-infiltrating CD8+ T cells." (PMID 37655662, 2023).
tumor (continued). "LPAR5 inhibition promotes effector memory CD8+ T cells and represses tumor growth and metastasis when combined with anti–PD-1." (PMID 37655662, 2023). "It has been reported that binding of LPA to tumor cells LPAR1 promotes tumor invasion, and the combination of LPA with platelets LPAR5 regulates platelet aggregation." (PMID 35659308, 2022). "With both tumor cells and TAM expressing similar levels of LPAR1 and LPAR2, LPAR3 was predominantly expressed in tumor cells, while LPAR5 and LPAR6 were selective for TAM." (PMID 32397679, 2020). "It was only later that we discovered that LPAR5 is abundantly expressed in murine and human CD8+ T cells and functions as an inhibitory receptor that blocks the anti-tumor actions of effector CD8+ T cells." (PMID 32397679, 2020). "In tumor cells, LPAR1, LPAR2, and LPAR3 are the major subtypes, while LPAR5 and LPAR6 are expressed only at very low levels in a subset of patients, if at all." (PMID 30353652, 2019). "LPA in ascites apparently targets tumor cells and TAMs via specific receptors, since LPAR1 and LPAR2 are expressed at similar levels by both cell types, LPAR3 is selective for tumor cells, LPAR5 and LPAR6 for TAMs." (PMID 27215396, 2016). "We hypothesized that LPAR5 might affect the composition of immune cells and stromal cells in TME, thus affecting tumor development." (PMID 36591220, 2022). "Non-small-cell lung carcinomas also display high expression of LPAR5, which in turn positively regulates myeloid/lymphoid or mixed-lineage leukaemia, translocated to 11 (MLT11), to stimulate proliferation and migration in vitro as well as tumour growth in vivo." (PMID 38607068, 2024). "On the other hand, the inhibition of LPAR4 and LPAR5 could not have a beneficial effect due to their inhibitory activities on tumor cell growth and motility." (PMID 39062979, 2024). "Thus, we first used an orthotopic tumor model to investigate how Lpar5 modulates CD8 T cell exhaustion, however, we did not observe any significant difference in CD8 T cell exhaustion markers in this model." (PMID 37270644, 2023). "As a result, we speculate that LPAR5 might enhance phagocytosis and antigen presentation of macrophages, recruiting more CD8+ T cells and CD4+ activated memory T cells to infiltrate the tumor microenvironment and inhibiting tumor cell growth." (PMID 36591220, 2022). "LPAR5 belongs to the non-EDG family and might act as a tumor suppressor." (PMID 36591220, 2022).
cancer (28 papers, 2014 to 2025). A tumor composed of atypical neoplastic, often pleomorphic cells that invade other tissues. "There were significant differences in PFS among the three cancers, among which high expression of LPAR5 was associated with better prognosis of ACC but with poor prognosis of LGG and PRAD." (PMID 37037831, 2023). "There were significant differences in DFS between the two cancers, among which high expression of LPAR5 was associated with better prognosis of UCEC, but with poor prognosis of KIRP." (PMID 37037831, 2023). "There were significant differences in the DSS of the three cancers, among which high expression of LPAR5 was associated with better prognosis in SKCM and THCA, but with poor prognosis in LGG." (PMID 37037831, 2023). "Although LPAR5 signaling is clearly associated with cancer initiation, progression and metastasis, whether and how LPAR5 is involved in IR-induced EMT and radiosensitivity of cancer cells remain unclear." (PMID 36199069, 2022). "Our data suggest that LPA signaling through Lpar5, which would be heightened in individuals with certain cancers, results in dysfunctional metabolism unable to sustain the energy required for optimal antigen-specific killing." (PMID 37270644, 2023). "GSEA was conducted according to the expression of LPAR5, and 8 and 15 cancers were significantly enriched in GO and KEGG, respectively." (PMID 37037831, 2023). "We then investigated the correlation between LPAR5 expression levels and the immune and molecular subtypes of the 33 cancers." (PMID 37037831, 2023). "Future studies should investigate how LPA, ATX, and LPAR5 signaling modules CD8 T cell phenotypes in these cancer types." (PMID 37270644, 2023). "Regarding LPAR2, its highest expression was in cancer epithelial cells followed by normal epithelial cells, and LPAR5 expression was highest in myeloid cells followed by B-cells." (PMID 37372960, 2023). "The expression levels of LPAR5 differed among the 33 cancer types, with the highest expression level in THCA and the lowest expression level in LIHC." (PMID 37037831, 2023). "Spearman analysis was used to evaluate the correlation between LPAR5 expression levels and TMB according to the mutation data of the 33 cancers." (PMID 37037831, 2023). "The expression of LPAR5 was found to have the same function or enrichment of pathways in different types of cancer by GSEA analysis; for example, the adaptive immune response was enriched in LGG, PRAD, SKCM, and UVM." (PMID 37037831, 2023). "To explore the effects of LPAR5 on the proliferation phenotype of cancer cells, we knocked down LPAR5 in HeLa cells and A549 cells with specific siRNA molecules and found that the proliferation of both cell lines was significantly suppressed." (PMID 36199069, 2022). "The expression between lysophosphatidic acid receptor-5 (LPA5) and cancer progression has been the subject of debate." (PMID 33050301, 2020). "LPAR4 (P2Y9/GPR23) and LPAR5 (GPR92) in cancer cells demonstrate inhibitory effects on proliferation and migration/invasion, which is in contrast to the effects of LPAR1–3." (PMID 32887262, 2020). "We then explored differences in the immune and molecular subtypes of LPAR5 in various human cancers, and the results showed that there were indeed differences in various cancers, which also proved that LPAR5 may be a potential biomarker for pan-cancer." (PMID 37037831, 2023). "In this study, we explored the prognostic and immunotherapeutic value of LPAR5 in pan-cancer." (PMID 37037831, 2023). "LPAR5 may be a potential biomarker for multiple malignancies and may provide a new target for cancer immunotherapy." (PMID 37037831, 2023). "Moreover, the expression level of LPAR5 varied among the different immune types in each cancer type." (PMID 37037831, 2023). "However, pan-cancer analysis also found that high LPAR5 expression predicted a worse prognosis in LGG, OV and PAAD." (PMID 36591220, 2022).